AR (androgen receptor)
Diseases named in the same sentence as AR in open-access papers (continued):
Sharing a sentence is not in itself a finding about the gene and the disease.
tumor (continued). "While all AR inhibitors approve by the FDA target the ligand-binding domain (LBD) of AR to prevent AR from activation, tumor cells develop therapy-resistance by either overexpressing AR or synthesizing AR splice variants or drug-resistant AR mutants to resume AR signaling." (PMID 33598437, 2020). "In ER-negative tumours, AR positivity was associated with worse DFS (p = 0.036)." (PMID 32928183, 2020). "Elevated PIK3CA protein activity in AR+ TNBC (through amplification and mutation) will bypass the AR-mediated PTEN up-regulation so that targeting AR alone may promote tumor growth by lowering PTEN expression and motivating the PI3K pathway." (PMID 32982970, 2020). "Moreover, we studied the underlying mechanisms of AR-pathway activation on docetaxel treatment efficacy by examining docetaxel tumour accumulation, target engagement and cell death induction." (PMID 32989230, 2020). "However, their data further suggested that relatively low expression of SGK1 is associated with higher tumor grade and increased cancer recurrence (adjusted log-rank test P = 0.077) and is a potential indicator of aberrant AR signaling in these tumors." (PMID 33542904, 2020). "The anti-tumor effect of arctigenin was associated with its dual actions on both tumor itself to control dysregulated tumor signaling like AR and Nkx3.1 and on adipose tissues to reduce the secretion of pro-cancer adipokines/cytokines as well as the release of free fatty acid." (PMID 31996731, 2020). "Moreover, The STING pro-inflammatory signaling cascade activated by the loss of AR function is a critical determinant of tumor infiltration by immune cells." (PMID 33076397, 2020). "As a coactivator of the AR, p300 is involved in many biological processes such as differentiation, proliferation, and cell cycle regulation and has already been associated with tumor progression and poor prognosis." (PMID 31951590, 2020). "Although we did not analyse whether this can result in AR transcriptional block, this phenomenon could be responsible for the loss of AR expression and a consequent development of tumour hormonal independence." (PMID 30628163, 2019). "Conversely, another group demonstrated that androgen pathways are associated with reduced aggression TNBC, and that AR loss may have a role in the progression of the tumor." (PMID 30941159, 2019). "Tumor slices retained morphology six days post IR-exposure, while treatment with apalutamide resulted in tissue integrity loss and loss of AR expression, and significantly reduced tissue slice viability with a reduced fraction of synthesis (S)-phase cells and increased number of apoptotic cells." (PMID 31635359, 2019). "Alterations of AR activity through mutation, amplification, overexpression, or cross-talk between AR and other growth factor pathways directly contribute to tumor progression and CRPC development." (PMID 30677079, 2019). "We also found genes associated with unique normal and tumor AR peaks." (PMID 31520575, 2019). "Interestingly, in one of the CR metastatic tumours, complete loss of AR pathway activity was associated with a relatively high NFκB score, which fits an inverse relationship between these pathways (sample GSM74888)." (PMID 30733525, 2019). "Furthermore, several analyses of circulating tumor DNA (ctDNA) in patients showed that AR gene amplification was associated with resistance to treatment with second-generation ARAT agents." (PMID 30248934, 2018). "In BC circulating tumor cells (CTCs), an active splice variant of AR, AR-v7 is expressed." (PMID 30210453, 2018). "Activation of the altered androgen biosynthesis pathway in a tumor, amplification and overexpression of the AR gene, genetic mutation of the AR, constitutively active AR splice variants, and phosphorylation of the AR by the Src and Akt pathways have been reported as possible mechanisms." (PMID 30248934, 2018).
tumor (continued). "Our work suggests that in SPRY2‐deficient tumours IL6 may mediate AR‐dependent CRPC formation by facilitating tumoral androgen biosynthesis, at least in part through enhanced androgen biosynthesis." (PMID 29540470, 2018). "Of note, among the genes implicated in prostate carcinogenesis and resistance to therapy, such as matrix metalloproteinase (MMP)-11, androgen receptor, and interleukin (IL)-17 receptor beta, were genes coexpressed by tumor-associated fibroblasts and tumor cells." (PMID 29380085, 2018). "In addition, AR amplification and AR specific mutations in circulating tumor DNA have also shown some promise for future treatment stratification." (PMID 29134562, 2018). "Some studies also revealed association of AR expression with good prognostic features and better disease free survival; however, we didn’t found any significant association of AR expression with various pathologic parameters like tumor stage and nodal metastasis." (PMID 29747687, 2018). "In CRPC, AR mutations are found in 5–30% of tumors, circulating tumor cells (CTCs), and ctDNA." (PMID 30248934, 2018). "Furthermore, AR loss suppresses tumor formation after deletion of the Pten tumor suppressor in CARNs; however, combined Pten deletion and activation of oncogenic Kras in AR-deleted CARNs result in tumors with focal neuroendocrine differentiation." (PMID 29334357, 2018). "Univariate analysis showed a significant association between RFS and tumour size (p < 0.001), nodal involvement (p < 0.001), adjuvant chemotherapy (p = 0.005), AR status (p = 0.034), AR/FOXA1 co-expression (p = 0.020), TILs density (p = 0.002) and PD-L1 expression by TILs (p = 0.018)." (PMID 29880907, 2018). "Interestingly, Smad4cKO prostate tissue displayed normal features when stained for β-catenin, Ki67, CK8, CK14, cyclin D1, and AR, indicating that loss of both tumor suppressors is required to cause this observed phenotype." (PMID 29113300, 2017). "Meanwhile, AR expression was shown to correlate with the risk of tumor progression." (PMID 28241422, 2017). "We therefore tested whether AR loss affects tumour initiation from basal and luminal cells under this condition." (PMID 28112153, 2017). "Notably, Pten loss can override AR-loss effects in both basal and luminal compartments to initiate tumours." (PMID 28112153, 2017). "Moreover, tumours initiate expression of AR splice-variants that cannot be targeted by novel anti-androgens." (PMID 28241429, 2017). "This may demonstrate the absence of finasteride or dutasteride treatment-associated effect in TRAMP mice large tumor AR expression." (PMID 28765837, 2017). "Two studies indicated a correlation between AR positivity and a lower risk of tumor recurrence." (PMID 28241422, 2017). "We hypothesize that the combination of up-regulation of AR expression early in the model with hormone cycling resulted in loss of the tumor phenotype in our model." (PMID 29113300, 2017). "We hypothesized that AR positivity would be associated with overall favorable tumor characteristics and prognosis and that analyses stratified by tumor ER status would reveal a differential role of AR depending on ER." (PMID 28643022, 2017). "In the discovery cohort (n = 209), moderate to high PD-L1 expression in prostatectomy specimens was associated with tumor progression (Ki-67, p < 0.001), Gleason score (p = 0.004), AR expression (p < 0.001), and was prognostic for biochemical recurrence (HR = 2.37; 95% CI, 1.32–4.25; p = 0.004)." (PMID 28604629, 2017). "However, further studies, potentially with assessment of tumor AR expression, are needed to fully evaluate the association of AR modulation with response to SPT." (PMID 29210989, 2017). "Thus, our results suggest that TRX1 is critical for preventing tumor-suppressive outcomes resulting from CRPC-associated inappropriate AR function in a low androgen environment." (PMID 29089489, 2017).
tumor (continued). "The current more intensive androgen deprivation treatments in CRPC, including abiraterone or enzalutamide, may thereby further select for gain-of-function AR mutations to allow the restoration of AR signaling in tumor cells." (PMID 28036278, 2017). "Enhanced AR downstream signaling caused by aberrant activation of AR variants such as AR-V7, hypersensitivity to androgens, overexpression of AR and intratumoral steroidogenesis are assumed to drive the tumor for progressing into this lethal state." (PMID 28783103, 2017). "BRCA1 expression tended to be lower in older age and in patient with positive family history however, the associations (with basal markers, tumor grade, AR, hormone receptors, bcl2 and Ki67 index) persisted after adjusting for age at diagnosis and family history." (PMID 28863181, 2017). "In addition, the recent Robinsonet al. paper highlighted that 71.3% of metastatic CRPC tumours carried AR pathway mutations, the majority in the AR itself but others in e.g. AR cofactors (NCoR1/2) and, again, the pioneer factor FOXA128." (PMID 27408704, 2016). "Several studies have shown that AR splice variants are expressed in PCa tumor samples." (PMID 27487144, 2016). "Although our findings show that AR expression is associated with low grade tumors, it may, analogous to ERα, still be a driver for tumor growth and therefore a potential therapeutic target." (PMID 27384477, 2016). "Since de novo tumorigenesis might be one of the causes of BC recurrence, we also investigated associations between AR/ERα/ERβ expression in corresponding normal urothelial tissues and tumor recurrence." (PMID 26885620, 2016). "In case 7, the long allele of the AR was inactivated in both tumor A and tumor B (pattern L)." (PMID 25882744, 2015). "In our previous work with heterogeneous CRPC tumors and cell lines, we showed that high-level AR-V expression, either concurrent with or exclusive from full-length AR, can often be ascribed to sub-clonal populations of tumor cells harboring underlying AR gene rearrangements." (PMID 25908785, 2015). "PSAP is a purported AR activator associated with metastatic potential in a number of neoplasms." (PMID 26341737, 2015). "In case 1, the short allele of the AR was inactivated in both tumor A and tumor B (pattern S)." (PMID 25882744, 2015). "However, re-expression of active Notch1 or PIP in Met1 tumor cells rescued the growth deficit in a Postn-null environment, suggesting that the loss of Postn selects for an AR-dependent pathway." (PMID 25592291, 2015). "In the previous report, Ack1-induced phosphorylation of AR at Tyr-267 was linked to activation of full length AR and xenograft tumor growth in castrated animals; expression of the full length AR Y267F mutant inhibited Ack1-driven, castrate resistant xenograft tumor growth." (PMID 25950519, 2015). "In Protocol 2, expression of the AR variants in each tumor type will be confirmed by Western Blot." (PMID 26401448, 2015). "However, when ordinal regression analyses including the Ki67 index into account were undertaken, a significant interaction between AR-IR and ErbB2-IR with respect to their association with the tumour stage was found." (PMID 25215939, 2014). "Notably, direct examination of human CRPC tumors showed that in situ metastases demonstrate a patient-specific range of tumor androgen levels and associated differences in AR expression similar to that observed in LuCaP35 and LuCaP96 xenografts." (PMID 25356728, 2014). "To further examine tumor characteristics associated with response to pre-receptor AR pathway inhibition, we determined whether response to treatment was related to tumor size at initiation of therapy." (PMID 25356728, 2014). "However, the finding that expression of AR in ERα− tumors was associated with increased age, postmenopausal status, lower tumor grade, smaller tumor size, and significantly improved disease-free survival suggests otherwise." (PMID 24324894, 2013).
tumor (continued). "Blood-based assays for AR mutation detection may be a compelling alternative, based on recent success in detection of tumor-specific mutations in circulating plasma DNA from patients with other cancers." (PMID 23580326, 2013). "Clonal analysis techniques, including T-cell and B-cell receptor gene rearrangement and one technique based on X-chromosome inactivation mosaicism and polymorphisms at the PGK and AR loci in female somatic cells, play an important role in differentiating neoplasm from reactive hyperplasia." (PMID 23958352, 2013). "Other AR signaling component genes, identified in the comparison of AA cancer versus AA patient-matched normal, have also been functionally linked to tumor progression." (PMID 23365759, 2013). "Recent studies suggest that constitutively active AR variants could play a role in tumor progression." (PMID 23658830, 2013). "AR signals have also been implicated in bladder carcinogenesis and tumor progression." (PMID 22922989, 2012). "Interestingly, in our study long CAG repeat sequence was associated with increased AR expression appeared in the tumor tissue and the rate was 90%." (PMID 23272232, 2012). "Androgen receptor genetic changes leading to aberrant functioning of the AR pathway may underlie the development of resistance to castration, allowing tumor cells to avoid the normal stimuli to growth." (PMID 23133437, 2012). "This study also restricted analysis to CRPC specimens from patients that had been treated with bicalutamide and/or flutamide, which may provide stronger selective pressure for emergence of tumor cells harboring AR point mutations." (PMID 22956944, 2012). "The fact that tumour cells retained the ability to express AR implicated androgens in PCa growth." (PMID 19888222, 2009). "However, a detailed study by this group showed that only 10% of surveyed samples of tumor tissue from patients with androgen independent disease demonstrated AR mutations." (PMID 18986533, 2008). "We also conclude that caspase 2, in an AR-dependent fashion, may be a specific intracellular switch for the regulation of the susceptibility of tumour cells." (PMID 17262078, 2007). "Alternatively, HER2 overexpression may play a role in hormonal escape in only a subset of tumours, since other potential mechanisms, such as increased AR expression or mutations in the AR, have also been described." (PMID 17211467, 2007). "Tumor-associated AR activity negatively correlates with immune infiltration and immunotherapy response across cancers, independent of sex, suggesting that combining AR inhibitors with checkpoint blockade may benefit patients with immunotherapy-refractory tumors." (PMID 41486951, 2026). "Furthermore, the absence of PTEN loss may contribute to a more immunologically active tumour microenvironment fostering the possibility of exploring immunotherapies, including immune checkpoint inhibitors, potentially in combination with AR-targeted therapies." (PMID 40165885, 2025). "Subsequent expression analysis of key oncogenic and tumor suppressor miRNAs demonstrated that andrographolide induced the upregulation of miR-16-5p, miR-34a-5p, and miR-200a-5p miRNAs implicated in apoptosis, proliferation control, and androgen receptor signaling." (PMID 41465187, 2025). "Furthermore, NRG1 also activates tumor-associated fibroblasts (CAFs) or immune cells through paracrine mechanisms, promoting local androgen synthesis or inflammatory cytokine release, thus indirectly sustaining AR activity." (PMID 40740239, 2025).
tumor (continued). "Resistance to ADT may be caused by several mechanisms linked to androgen signaling, including androgen production within the tumor itself or by the adrenal glands, AR gene amplification or overexpression, the presence of AR mutations, and the development of constitutively active AR splice variants." (PMID 41228300, 2025). "However, tissue microarrays (TMAs) were utilized, which may have caused sampling errors due to tumor heterogeneity, contributing to the failure to detect a prognostic effect of AR expression." (PMID 39851328, 2025). "Ascl1 loss in established NEPC results in transient tumor regression followed by recurrence; however, Ascl1 deletion prior to transplantation completely abrogates lineage plasticity, yielding adenocarcinomas with elevated AR expression and marked sensitivity to castration." (PMID 38645223, 2024). "The aim of this study was to investigate whether tumour-derived AR mutations in the plasma of patients with PCa are primarily present in EV DNA or cfDNA and to determine which target exhibits higher sensitivity in detecting AR mutations." (PMID 39535155, 2024). "Interestingly, dysregulation of the AR has been implicated in modulating tumor metabolism." (PMID 39585048, 2024). "Moreover, AR has a higher mutation frequency in patients with advanced PCa, and studying AR mutations alone cannot fully reflect the advantages of EV DNA in early-stage tumours." (PMID 39535155, 2024). "AR expression has been observed in various subtypes of OC and its activation has been linked to tumor growth and poor prognosis suggesting that targeting AR signaling, especially with AR antagonists such as enzalutamide, might represent a potential therapeutic strategy for OC." (PMID 38750579, 2024). "We proposed that population-dependent differences in the biological effects of AR depend on differences in potential modifiers, such as AR splice variants, epigenetic factors, or tumor microenvironment, which may affect patient prognosis and response to AR-targeted agents." (PMID 37099044, 2023). "Moreover, ERα and AR in malignant colonic samples showed significant direct associations with tumor size, N stage, numbers of positive regional lymph nodes, and late-stage neoplasms in males, as well as female patients." (PMID 37206439, 2023). "As AR overexpression and mutations are also detected in the majority of mCRPC patients, increasing attention has been given to the molecular mechanisms underlying the reciprocal crosstalk and feedback mechanisms between these two pathways and their role in tumor progression." (PMID 36768610, 2023). "Furthermore, the alterations in the [CAG]n repeats of the AR gene are also associated with poor outcomes in male patients with oral cavity or oropharyngeal cancers; shorter repeats (≤20) were correlated with a more aggressive tumor subset." (PMID 36835177, 2023). "However, a high AR:ER ratio is associated with the development of resistance to treatment, which suggests that the expression level of both receptors could influence tumor growth." (PMID 37894767, 2023). "We then investigated whether tumor mRNA and protein levels of AR are positively associated." (PMID 36833272, 2023). "Therefore, the mutated AR can be activated also by steroid hormones and lead to tumor growth." (PMID 38068717, 2023). "This indicates that deficiency of this crucial tumor suppressor might act cooperatively with therapeutic AR blockade to upregulate stress response pathways, which finally activate survival mechanisms of cancer cells via NF-κB-mediated induction of antiapoptotic genes." (PMID 36551650, 2022). "Using this approach, we showed that inhibition of oxidative phosphorylation significantly reduced tumor viability and caused apoptosis in two independent AR-positive LuCaP models, suggesting mitochondrial metabolism as a therapeutic vulnerability in AR-positive CRPC." (PMID 35406510, 2022).